SNORD114-23 (small nucleolar RNA, C/D box 114-23)
Synonyms: 14q(II-23)
Gene: Small nucleolar RNA gene on chromosome 14 (100,983,876 to 100,983,947, forward strand). Ensembl gene ENSG00000200406.
Gene Ontology:
Biological process: RNA processing
Cellular component: nucleolus
Homologues: Orthologues: mouse Gm22205 (68% identical). Paralogues in human: SNORD114-28 (93% identical), SNORD114-9 (93% identical), SNORD114-15 (92% identical), SNORD114-20 (92% identical), SNORD114-22 (92% identical), SNORD114-26 (92% identical), SNORD114-5 (92% identical), SNORD114-21 (90% identical), SNORD114-25 (90% identical), SNORD114-29 (89% identical), SNORD114-3 (89% identical), SNORD114-27 (86% identical), and 26 more.